INS (insulin)
Diseases named in the same sentence as INS in open-access papers (continued):
Sharing a sentence is not in itself a finding about the gene and the disease.
diabetes (continued). "Diabetes mellitus (DM) is a metabolic disturbance that is characterized by dysfunction in the secretion and response to insulin." (PMID 27525285, 2016). "Although diabetes and PanNETs represent an opposite end of the spectrum with respect to blood glucose levels, the level of secreted insulin is crucial in both conditions." (PMID 26824039, 2016). "BBR is also an effective anti-diabetes agent.BBR significantly lowered fasting blood glucose (FBG), hemoglobin A1C, triglyceride, and insulin levels in patients with type 2 diabetes mellitus (T2DM) in the clinical study." (PMID 27629750, 2016). "Diabetes mellitus (DM) is a metabolic disease resulting in hyperglycemia, either becauseof the low insulin levels or due to insulin resistance." (PMID 27508899, 2016). "Diabetes develops in Pdx1-haploinsufficient mice due to an increase in β-cell death leading to reduced β-cell mass and decreased insulin secretion." (PMID 27137932, 2016). "Individuals with insulin resistance require increasing levels of insulin to maintain normal glucose levels and are likely to progress to type 2 diabetes mellitus." (PMID 27275336, 2016). "A small percentage of diabetes is monogenic and is manifested early in life; defects affect the production/processing of insulin precursor." (PMID 27602200, 2016). "Increasing level of insulin and HOMA IR are associated with HAART and risk of diabetes; however, surprisingly there was an improvement in HOMA of beta-cell function derived from insulin." (PMID 26789842, 2016). "TNF-α has been suggested to participate in the development of diabetes by impairing insulin actions." (PMID 27013528, 2016). "Conversely, experimental inhibition of peripheral insulin signaling (a model of diabetes) impairs memory, while treatments that enhance insulin sensitivity improve memory deficits." (PMID 30202553, 2016). "He had a 30-year history of type 2 diabetes mellitus and an approximately 6-year history of insulin injection administration, with an average glycated hemoglobin (HbA1c) level of 7.0 %." (PMID 27456688, 2016). "As insulin is only prescribed for the treatment of diabetes, the majority of regional variation will reflect differences in the prevalence of mainly type 1 but also type 2 diabetes and differences in the severity of type 2 diabetes." (PMID 27192491, 2016). "Insulin-specific B cells fulfill this requirement for diabetes, though little is known regarding the affinity of this BCR-antigen (Ag) interaction." (PMID 27834793, 2016). "For decades, several approaches have been developed for the treatment of diabetes including insulin-secretion stimulants, improving insulin preparations, and islet transplantation, yet many unexamined avenues of research remain." (PMID 26901059, 2016). "Vitamin E reduces protein glycation and improves insulin sensitivity, while cumin is effective in remission of diabetes." (PMID 28357199, 2016). "Due to the fact that it acts as an insulin secretagogue in the presence of elevated blood glucose concentrations, it has been proposed for the potential treatment of insulin resistance, diabetes and obesity." (PMID 27879673, 2016). "Diabetes was induced via multiple low-dose injections of streptozotocin and blood glucose was maintained at moderate hyperglycemia (9–17 mM) through insulin supplementation." (PMID 26885531, 2016). "It was shown that the GLP-1 response was impaired in individuals with pre-diabetes and diabetes type 2 (up to 25%) compared to NGT, and an increase of GLP-1 was positively associated with improved insulin sensitivity." (PMID 26990559, 2016). "We found significant relationships between age, duration of diabetes, glycemic control, insulin dose and all microvascular complications." (PMID 27842589, 2016). "It is better to consider the conjunctive application of a lipid-reduced drug for the clinical use of insulin in diabetes patients with NAFLD." (PMID 27104558, 2016).
diabetes (continued). "Diabetes mellitus is a metabolic disorder of multiple aetiology characterised by hyperglycemia resulting from defects in insulin secretion, insulin action or both." (PMID 27846886, 2016). "It is certainly understood that diabetes, itself, creates tremendous strain on the ecosystem of a family unit with intensive insulin regimens, constant food mindfulness, and the irrevocability of living with a chronic illness." (PMID 26793242, 2016). "OM has long been recognized as a healthy breakfast choice for patients with diabetes for having high fiber content, which is known to improve glycemic control and enhance insulin response in patients with type 2 diabetes." (PMID 27455318, 2016). "Recurrent insulin-induced hypoglycaemia is a major limitation to insulin treatment in diabetes patients leading to a condition called hypoglycaemia-associated autonomic failure (HAAF)." (PMID 27843452, 2016). "On the other hand, diabetes duration and body mass index are influenced by the factors insulin secretion and insulin resistance, respectively." (PMID 26849676, 2016). "The resultant cell population secreted insulin in response to glucose at concentrations within the physiological range, and prevented the onset of diabetes when implanted in a diabetic mouse model." (PMID 27243814, 2016). "In diabetic rats, in which diabetes was induced by alloxan, fucoidan from Saccarina japonica reduced blood glucose levels, which was accompanied by increased serum insulin levels and altered plasma lipid levels." (PMID 26848666, 2016). "Since PPARγ plays an important role in adipogenic differentiation and is a receptor for insulin sensitizing drugs, regulation of its expression is of importance with respect to nutrition, obesity and diabetes." (PMID 26797605, 2016). "This meant that, to be included, a patient required an accurate diagnosis of diabetes and at least one prescription of insulin." (PMID 27861488, 2016). "Abnormalities of islet cell function in diabetes include an impaired insulin response to stimulus, a reduced number of β cells, and an inappropriate glucagon response." (PMID 27572106, 2016). "Sulphonylureas have been used to treat diabetes by increasing insulin secretion by closing KATP-channels to trigger calcium influx." (PMID 26978400, 2016). "As for the duration of diabetes, patients in studies using insulin as the combination therapy suffered longer than others." (PMID 27600598, 2016). "Four, the global (this study) or hepatocyte-specific overexpression of miR-155 in mice does not induce weight gain, avoiding the major side effect of increasing insulin sensitivity for diabetes therapies." (PMID 27711113, 2016). "Among 29 patients with PAOD and diabetes, 22 patients took insulin, 17 patients took biguanides, and four patients took derivatives of sulfonylureas." (PMID 27834825, 2016). "Impaired glucose tolerant subjects have increased C14:0, C17:0 and C18:0 fatty acids levels and C14:0, C17:0, C18:0 and C20:1 levels are increased in diabetics compared to insulin sensitive subjects." (PMID 26770180, 2016). "In the present study therefore, we conducted a nationwide survey of diabetic patients with GADAb who had had non-insulin-requiring diabetes more than 5 years after the diagnosis, under the auspices of the Japan Diabetes Society." (PMID 27177031, 2016). "Clinically, where the type of diabetes is unclear, giving insulin from diagnosis is a rational decision to avoid the potential consequences of untreated type 1 diabetes, such as ketoacidosis." (PMID 27080317, 2016). "As for the treatment of diabetes 61.5% of the patients were treated with insulin, 38.5% with oral diabetes medications, and 11.5% with both insulin and oral diabetes medications." (PMID 27814399, 2016). "This animal model together with the insulin dosing regimen is suitable to address diabetes-induced early diabetic nephropathy and also to study combination therapies with insulin for the treatment of type 1 diabetes." (PMID 27253523, 2016).
diabetes (continued). "We provide a systematic framework for assessing the contribution of gene candidates to insulin-secretion or insulin-resistance pathways relevant to diabetes pathogenesis." (PMID 27053133, 2016). "Diabetes mellitus is a group of metabolic diseases characterized by hyperglycemia resulting from defects in insulin secretion, insulin action, or both." (PMID 26881245, 2016). "We found inverse independent correlations between MCRI and hepatic lipase (P = 0.0004), insulin secretion (P = 0.0002), alanine aminotransferase (P = 0.0045), total fat mass (P = 0.014), and diabetes (P = 0.03)." (PMID 27846285, 2016). "In this study, we examine the associations of premorbid intelligence vs. current cognition with body mass index (BMI), insulin and diabetes in elderly adults." (PMID 27642517, 2016). "Approximately one fourth of patients especially in long lasting diabetes group were on insulin treatment (mostly insulin analog)." (PMID 27246619, 2016). "Diabetes treatments including oral hypoglycemic agents (OHAs) and insulin that minimize disease symptoms and potentially prevent complications such as cognitive decline are of growing importance." (PMID 27195294, 2016). "In the United Kingdom Prospective Diabetes Study (UKPDS) major hypoglycemia occurred in 2.3 % of patients per year who were treated with insulin compared with rates of 0.6 % in those on sulfonylurea therapy." (PMID 27278922, 2016). "Before the discovery of insulin and other blood glucose lowering agents, traditional herbal remedies were used to treat diabetes and related complications." (PMID 27047810, 2016). "The study also demonstrates the prominence of hypoglycemia in the CKD population where diabetes is common along with the use of insulin and other diabetic treatments." (PMID 27230267, 2016). "PPARγ ligand rosiglitazone has been successfully used as insulin-sensitizing drugs in patients with type 2 diabetes mellitus and exerts beneficial effects on the kidney to ameliorate proteinuria and inflammation." (PMID 27145370, 2016). "The most common type, the type 2 diabetes mellitus, constitutes of 90–95 % of the cases and is characterized by the action of and/or impaired insulin secretion." (PMID 26889209, 2016). "Consumers often inquire about a variety of insulin therapies in social Q&A, while blogs often include recipes specific to the use of vinegar, a popular ingredient in diabetes-controlling food." (PMID 27884812, 2016). "If this compensatory increase in insulin secretion fails, plasma glucose levels rise leading to diabetes." (PMID 27861636, 2016). "Insulin therapy is a primary method to treat diabetes, which can further prevent diabetic cardiac damage." (PMID 27376265, 2016). "In all WAT depots studied, FNDC5 gene expression enhanced with diabetes, and these values decreased significantly (even over control values) after insulin treatment." (PMID 27432282, 2016). "To further explore the effects of altered Inpp5f in the context of diabetes, we mainly focused on Akt activity and glucose uptake, the key molecular and cellular readouts of insulin signaling." (PMID 26908121, 2016). "Impaired insulin secretion and/or insulin action emanate from diabetes mellitus increased levels of TNF-α and IL-6." (PMID 27338453, 2016). "Serum insulin levels decreased about 70 % in NIA/STZ-induced diabetes (p = 0.001) and about 97 % in STZ-induced diabetes (p < 0.001), compared with non-diabetic control rats." (PMID 26877773, 2016). "Essential diabetes drugs such as insulin, metformin, glibenclamide, protamine zinc insulin, and glipizide are included in the national drug list to which all publicly insured patients have access." (PMID 27760677, 2016). "Insulin delivery is crucial for diabetics to maintain BGLs, improve their quality of life and extend lifespans." (PMID 27792179, 2016). "Edward Albert Sharpey-Schafer announced that the pancreas of a patient diagnosed with diabetes was unable to produce what he called “insulin”." (PMID 27974926, 2016).
diabetes (continued). "In comparison, patients with type 1 diabetes mellitus had on average 3 % insulin secretion capacity on mixed meal tolerance testing when compared to healthy controls (p < 0.0001)." (PMID 26370678, 2016). "Maintaining glucose homeostasis and improving insulin sensitivity are important effects of LXRs that potentially influence the development of insulin resistance and diabetes." (PMID 26611207, 2016). "Metformin, a biguanide that acts as an insulin sensitiser, is the most commonly used oral hypoglycaemic agent in type 2 diabetes mellitus." (PMID 27531741, 2016). "PPAR-γ ligands decrease vasculature complications in diabetes, by lowering fasting insulin level and blood pressure, and reduce secondary clinical end point of stroke and myocardial infarction death." (PMID 27413253, 2016). "Subsequent research led to the concept of diabetes as a “two-hit” disease, involving both insulin resistance in muscle tissue, and failure of the pancreatic beta-cells to produce enough insulin to compensate for this resistance." (PMID 27458578, 2016). "The m.3423A>G mutation in the mitochondrial genome includes diabetes as one of its many phenotypic consequences; this diabetes also requires insulin treatment." (PMID 27330718, 2016). "Baseline combined group analysis demonstrated that pHDL activity was related with BMI, INS-0, blood glucose, HOMA, HDL-cholesterol, and TG, while it was associated with LDL-cholesterol in subjects with T2D, when diabetes was uncontrolled." (PMID 27567897, 2016). "Exercise training with PPARγ agonist is expected to increase glucose uptake and improve insulin sensitivity in skeletal muscle of patients with diabetes." (PMID 27508153, 2016). "GDM and Type 2 diabetes mellitus (T2D) have similar pathogenesis with impaired insulin secretion and increased insulin resistance." (PMID 27468700, 2016). "This study demonstrates that increasing age, higher household income, family history of diabetes, short sleep, and sedentary behavior contribute to increased fasting glycaemic and insulin levels in apparently healthy subjects as well." (PMID 27995147, 2016). "Diabetes is defined as a complex metabolic disorder that affects protein, carbohydrate and fat metabolism, all due to insulin insufficiency or insulin dysfunction." (PMID 27827864, 2016). "The evidence, favorable or unfavorable, to the use of insulin before overt diabetes in CF patients remains inconclusive, with little knowledge about long-term results." (PMID 26994743, 2016). "In the current study of a wide spectrum of traits from Mexican-American families, we identified diabetes, insulin secretion, hepatic lipase, total fat mass, ALT, and apolipoprotein A-I as independent factors associated with insulin clearance." (PMID 27846285, 2016). "In this study high blood glucose (P<0.0001), polydipsia, polyuria (wet cage), and reduced plasma insulin (P<0.002) were clear signs of diabetes in the CD group." (PMID 26459400, 2016). "Insulin is a relatively low-priced drug however, the chronic nature of Diabetes means the cost for insulin treatment is high, and together with an increasing number of patients, this financial burden challenges healthcare systems worldwide." (PMID 27907132, 2016). "Insulin resistance refers to the state of decreased insulin response and is a common feature of obesity, hypertension, diabetes, and coronary artery disease." (PMID 27413253, 2016). "One patient (patient 4) who began with some renal insufficiency improved his serum creatinine after 4 weeks while another patient with diabetes (patient 2) who was on insulin became insulin free within days." (PMID 27525031, 2016). "IGF-1 and insulin share major downstream regulation pathway and both are engaged in cancerogenesis and diabetes." (PMID 27405474, 2016). "On the fifth day of life, hyperglycemia (180 mg/dl) was noted, and the next day, the diagnosis of diabetes was confirmed (high blood sugar, glucosuria, undetectable levels of insulin and C-peptide)." (PMID 27909691, 2016).
diabetes (continued). "Diabetes is an endocrine disorder characterized by elevated blood glucose levels resulting from the defects in insulin-secretory response or resistance to insulin action." (PMID 27589714, 2016). "After multivariable adjustment on age, gender and medication (whenever necessary), the associations of ELC with BMI, abdominal obesity, hypertension, glucose and insulin levels, diabetes, HOMA-IR, and MS remained." (PMID 26790748, 2016). "Introducing oral hypoglycemic drugs in the early stage of diabetes before dependence on insulin proved beneficial in preliminary studies." (PMID 27872738, 2016). "Our study sample shows that age, use of insulin duration, and years of diabetes were similar to samples from other studies." (PMID 27994961, 2016). "Diabetes mellitus (DM) is a metabolic disorder characterized by chronic hyperglycemia due to an impairment of insulin secretion, defects of insulin action, or both." (PMID 27153943, 2016). "Since insulin resistant is one of main mechanisms of diabetes, we are still uncertain why the perfusion data differs between the two groups." (PMID 27552827, 2016). "Type 1 diabetes mellitus is a chronic inflammatory disease involving insulin producing β-cells destroyed by the conjoined action of auto reactive T-cells, inflammatory cytokines and monocytic cells." (PMID 27575603, 2016). "Swimming exercises accompanied by consuming UD aqueous extracts effectively improved diabetic parameters, repaired pancreatic tissues in streptozotocin-induced diabetics in vivo, and increased glucose uptake or insulin in UD-treated cells in vitro." (PMID 26980377, 2016). "Studies in humans and mice have postulated that the over replacement of insulin in patients with Diabetes produces a general anabolic effect that leads to increased fat accumulation and weight gain." (PMID 27777901, 2016). "Clinical reports have testified that long-term insulin usage in diabetes patients will lead to adverse reactions." (PMID 27212152, 2016). "Of the 23 patients with known diabetes, 13 were currently on oral antihyperglycemic drugs, 1 patient was using insulin only, and 8 received both oral drugs and insulin." (PMID 27807545, 2016). "Treatment of diabetes involves use of drugs that reduce glucose levels, including insulin and oral antihyperglycemic drugs." (PMID 27069932, 2016). "At the end of treatment, insulin level of blood was also measured and the results showed that the experimentally-induced diabetes lowered significantly (P<0.05) the insulin level." (PMID 27980584, 2016). "In the treatment group, one patient with known insulin-depe*ndent diabetes required hospitalization for hyperglycaemia." (PMID 27280398, 2016). "Accordingly, 28% were insulin sensitive and 72% were insulin resistant, including 25% with known type 2 diabetes mellitus." (PMID 27342408, 2016). "Over the past ~75 years, various strategies have been employed to provide basal insulin therapy for patients with diabetes." (PMID 27528391, 2016). "In total, 601 adults with insulin-treated diabetes and diabetes duration ≥5 years were recruited in Devon, Northamptonshire, and Leicestershire." (PMID 27080317, 2016). "Of these, hypertension and hyperlipidemia were the most sensitive, while factors relating to severity of diabetes—insulin use, poor glycemic control, and long duration of diabetes—all were relatively insensitive but considerably more specific." (PMID 26861208, 2016). "Insulin was also able to reverse the diabetes-induced changes in islet insulin content and glycogen, but took longer to do so." (PMID 27882918, 2016). "The abscess was initially refractory, despite tapering corticosteroid treatment, controlling diabetes by intensive insulin therapy, administration of antibiotics, and percutaneous abscess drainage." (PMID 27484098, 2016).